GREB1L (GREB1 like retinoic acid receptor coactivator)
Description:
Plays a major role in early metanephros and genital development.
Synonyms: C18orf6; KIAA1772; FLJ13687; DFNA80; RHDA3
Tractability: Antibody: UniProt predicts a signal peptide or a membrane-spanning region. PROTAC: ubiquitination databases record sites on it.
Gene: Protein-coding gene on chromosome 18 (21,242,229 to 21,526,112, forward strand). Ensembl gene ENSG00000141449.
Subcellular location: Membrane
Subcellular location (Human Protein Atlas): Mitochondria
Gene Ontology:
Biological process: kidney development; morphogenesis of an epithelium
Cellular component: membrane
Genetic constraint (gnomAD): Loss-of-function variants: 14 observed, 174.93 expected, observed/expected ratio (o/e) 0.08, 90% interval 0.052 to 0.12. The synonymous counts are far from expectation, so gnomAD's model fits this gene poorly and the ratio says little. Missense variants: 1,521 observed, 2,261.9 expected, observed/expected ratio (o/e) 0.67, 90% interval 0.64 to 0.7. Synonymous variants: 726 observed, 858.53 expected, observed/expected ratio (o/e) 0.85, 90% interval 0.8 to 0.9.
Homologues: Orthologues: chimpanzee GREB1L (99% identical), macaque GREB1L (99% identical), pig GREB1L (93% identical), rabbit GREB1L (93% identical), rat Greb1l (91% identical), mouse Greb1l (90% identical), guinea pig GREB1L (87% identical), tropical clawed frog greb1l (75% identical), zebrafish greb1l (63% identical). Paralogues in human: GREB1 (51% identical).
Diseases named in the same sentence as GREB1L in open-access papers:
GREB1L is named in the same sentence as 30 diseases in open-access papers, as found by Europe PMC text mining. Sharing a sentence is not in itself a finding about the gene and the disease. The quoted sentences say what the papers report.
renal agenesis (8 papers, 2021 to 2025). Renal agenesis (RA) is a form of renal tract malformation characterized by the complete absence of development of one or both kidneys (unilateral RA or bilateral RA respectively), accompanied by absent ureter(s). "In the majority of reported cases where GREB1L variants were identified in patients with bilateral renal agenesis, the mildly affected or unaffected mother is the carrier." (PMID 40041231, 2022). "Of note, all previously reported damaging mutations in GREB1L causing renal agenesis are either maternally inherited or occurred de novo." (PMID 35013161, 2022). "Mutations in GREB1L have been associated with a form of renal hypodysplasia/aplasia (RHDA3) (OMIM#617805), which is inherited in an autosomal dominant pattern and presents as early as fetal life." (PMID 40041231, 2022). "In a study of 183 unrelated families affected by various forms of CAKUT, 16 (8.7%) heterozygous pathogenic or suspected pathogenic variants in GREB1L were identified, 12 of which were found in 54 cases (25.8%) with bilateral renal agenesis in this cohort." (PMID 40041231, 2022). "In the previous reports, besides unilateral or bilateral renal agenesis, patients with RHDA3 caused by GREB1L mutations also had congenital hydronephrosis, ureter and bladder aplasia and vesicoureteral reflux in urinary system." (PMID 36371238, 2022). "In another study of 612 individuals affected by renal agenesis and hypodysplasia, 17 (2.8%) heterozygous pathogenic or suspected pathogenic variants in GREB1L were identified." (PMID 40041231, 2022). "Finally, one variant was identified in two related foetuses in the GREB1L gene, associated with renal agenesis, while in two other related cases, showing congenital heart malformations, a variant was identified in the NOTCH2 gene." (PMID 41153384, 2025). "The only two patients presenting significant lower levels of GREB1L mRNA relatively to healthy controls (p < 0.05) were MRKH type II (Patient 14 and 22), with unilateral renal agenesis." (PMID 34063745, 2021). "This revealed one pathogenic variant in twin 3-1 (affected) and twin 3-2 (renal agenesis without features of MRKH), carrying a stop variant in GREB1L (ENST00000269218.10):c.4665T>A, p.Tyr1555*." (PMID 36233463, 2022).
urogenital adysplasia (4 papers, 2020 to 2024). "In a Greb1l knock-out mouse, Müllerian ducts are missing and a study using whole-genome sequencing in patients with Müllerian agenesis found possible causative mutations in the GREB1L gene." (PMID 33763415, 2021). "Several studies associated variants in GREB1L to congenital kidney malformations/agenesis, urogenital adysplasia, and Mayer-Rokitansky‐Kuster‐Hauser syndrome suggesting its role in the functioning of the urogenital systems." (PMID 36357908, 2022). "Last, this renal/ear link is also seen in Mayer-Rokitansky-Kuster-Hauser (MRKH) syndrome, characterized by abnormal development of the internal reproductive system in females, and is also caused by GREB1L variants." (PMID 32585897, 2020). "In recent years, GREB1L variants have been identified as a major cause of MRKH syndrome, particularly in families with a hereditary urogenital adysplasia-like presentations." (PMID 38699388, 2024).
deafness (3 papers, 2024 to 2025). An inherited or acquired condition characterized by the complete loss of the ability to hear from one or both ears. "Of note, besides kidney and uterovaginal malformations, GREB1L variants have also been associated with inner ear malformations and deafness as well as complex congenital heart disease." (PMID 38699388, 2024). "We detected FGF3 (p.Arg165Gly) and GREB1L (p.Cys186Arg), variants of uncertain significance in two recognized genes for deafness, and PBXIP1(p.Trp574*) in a candidate gene." (PMID 38947059, 2024).
lung adenocarcinoma (3 papers, 2021 to 2025). A carcinoma that arises from the lung and is characterized by the presence of malignant glandular epithelial cells. "Recent bioinformatics research suggested that GREB1L was associated with immune regulation and methylation in gastric and lung adenocarcinoma." (PMID 37964281, 2023). "It is the first study to demonstrate the functional impact of GREB1L in lung adenocarcinoma." (PMID 34168239, 2021). "Moreover, GREB1L is a novel predictive and prognostic biomarker of gastric and lung adenocarcinoma." (PMID 37964281, 2023). "In the field of tumors, aberrant expression of GREB1L has been reported in breast, ovarian and prostate cancers, but its biological significance in lung adenocarcinoma is not clear." (PMID 40568599, 2025). "In recent years, several studies have suggested that genes such as SPRR1B, MFI2, LIPK, GREB1L, and GPR115 may play a potential role in lung adenocarcinoma (LUAD)." (PMID 40568599, 2025).
ear malformation (2 papers, 2020 to 2024). "Therefore, the number of ear malformations associated with GREB1L variants is likely under-reported." (PMID 32585897, 2020).
gastric adenocarcinoma (2 papers, 2021 to 2023). "Previous studies have shown that GREB1L plays a vital role in lung and gastric adenocarcinoma." (PMID 37964281, 2023).
male infertility (2 papers, 2022 to 2025). The inability of the male to effect fertilization of an ovum after a specified period of unprotected intercourse. "Similarly, GREB1L has recently been proposed as a marker for male infertility in mammals, and its paralog GREB1 is involved in estrogen-dependent functions of Sertoli cells." (PMID 40839421, 2025).
Autosomal Dominant deafness (1 paper, 2022). "GREB1L (OMIM: 617,782) is located on 18q11.1-q11.2 of the human genome and has been implicated in Autosomal Dominant deafness and renal hypodysplasia/aplasia." (PMID 36357908, 2022).
breast carcinoma (1 paper, 2023). "Therefore, we believe that GREB1L can affect the metastasis of breast cancer by regulating the EMT process." (PMID 37964281, 2023). "GREB1L is highly expressed in breast cancer tissues and breast cancer cells." (PMID 37964281, 2023). "The overexpression of GREB1L in breast cancer predicted a favorable prognosis." (PMID 37964281, 2023). "Moreover, to verify the effect of GREB1L on the metastasis ability of breast cancer cells in vivo, we detected the protein levels of epithelial-to-mesenchymal transition (EMT) marker genes, such as E-cadherin, N-cadherin, and vimentin, in tumors isolated from mice." (PMID 37964281, 2023).
congenital heart disease (1 paper, 2025). A heart disease that is present at birth. "Nonetheless, recent evidence indicates that GREB1L variants may contribute to complex congenital heart disease, including outflow tract anomalies such as tetralogy of Fallot and double outlet right ventricle, in patients." (PMID 41286922, 2025).
MRKH syndrome (1 paper, 2021). "Concerning GREB1L, recently, it has been designated as a gene frequently involved in hereditary urogenital dysplasia and as a significant contributor in MRKH syndrome, more precisely in the MRKH type II subgroup." (PMID 34063745, 2021). "We then focused our attention on the expression of other genes selected from the literature which are likely to play a role in MRKH syndrome phenotype determination: MUC1, HOXC8 and GREB1L." (PMID 34063745, 2021). "In order to establish a correlation between MRKH syndrome phenotype and gene expression pattern, we performed PCA on data from RT-qPCRs for PRKX, MUC1, HOXC8 and GREB1L loci." (PMID 34063745, 2021).
osteosarcoma (1 paper, 2023). A usually aggressive malignant bone-forming mesenchymal neoplasm, predominantly affecting adolescents and young adults. "The results showed that 79 DEGs affected the prognosis of osteosarcoma, with PDE4C, CFAP44, CARNS1, GREB1L, ROF207 identified as significant risk factors and GBP1, MSC, GBP3, F13A1, CCL2 as substantial protective factors." (PMID 37796192, 2023).
thyroid carcinoma (1 paper, 2023). "GREB1L expression was significantly lower in kidney chromophobe (KICH) (p = 8.9e-11) and thyroid carcinoma (THCA) (p = 2.9e-06) tissues than in normal tissues." (PMID 37964281, 2023).
type 2 MRKH syndrome (1 paper, 2022). "Recently, whole exome sequencing (WES) was used to identify GREB1L as a potential candidate for MRKH type 2 cases with kidney anomalies, but in general, the multifaceted and complex phenotype of the type 2 MRKH syndrome makes interpretation of genetic findings challenging." (PMID 36233463, 2022).
cancer (4 papers, 2018 to 2023). A tumor composed of atypical neoplastic, often pleomorphic cells that invade other tissues. "Growth regulation by estrogen in breast cancer 1 like (GREB1L), an estrogen-regulated gene, is a coactivator of the retinoic acid receptor (RAR) gene, the activation of which regulates the RAR pathway." (PMID 37964281, 2023). "The Cancer Genome Atlas database was used to compare the expression level of GREB1L between tumor and normal tissues." (PMID 37964281, 2023). "We found that the expression of GREB1L in the cancer tissue was significantly higher than that in the paracancerous tissue." (PMID 37964281, 2023). "The results showed that high GREB1L expression was upregulated in the Cell cycle, MicroRNAs in cancer, and JAK-STAT signaling pathway." (PMID 34168239, 2021). "Thus, our study provides new insights into understanding the potential roles of GREB1L in tumor microenvironment and its potential use as cancer therapeutic and prognostic biomarker." (PMID 34168239, 2021). "Interestingly, GSEA pathwayanalysis found that GREB1L is related to the cell cycle, microRNAs in cancer, JAK-STAT signaling pathway, cytokine-cytokine receptor interaction, Wnt signaling pathway, Ras signaling pathway, and cGMP-PKG signaling pathway." (PMID 34168239, 2021).
tumor (4 papers, 2021 to 2025). "To further explore the potential biological pathways of GREB1L that promote tumor progression, we also performed a GSEA pathway analysis." (PMID 34168239, 2021). "In contrast, that of GREB1L, a gene that suppresses tumor growth, was upregulated." (PMID 40062227, 2025). "GREB1L, as a co-activator of estrogen receptors, may drive tumor proliferation through hormone signaling pathways." (PMID 40568599, 2025). "Therefore, targeting GREB1L seems to be an alternative strategy for tumor therapy." (PMID 34168239, 2021). "Besides, GREB1L mediates immune cell infiltration in the tumor microenvironment." (PMID 34168239, 2021). "PCR results showed elevated expression of GREB1L, MFI2, SPRR1B, GPR115 and LIPK mRNA in LUAD tumor tissues." (PMID 40568599, 2025). "Although changes in GREB1L expression did not affect their proliferation and colony formation abilities in vitro and in vivo, they affected the expression of tumor metastasis-related genes in vivo." (PMID 37964281, 2023).
GREB1L also shares sentences with these, for which no sentence is quoted: renal hypodysplasia/aplasia 3 (2 papers); renal hypoplasia (2); cholangiocarcinoma (1); congenital heart malformation (1); congenital hydronephrosis (1); gastric cancer (1); kidney malformations (1); lung squamous cell carcinoma (1); pancreatic adenocarcinoma (1); paraganglioma (1); pheochromocytoma (1); polycystic kidney disease (1); Tetralogy of Fallot (1); vesicoureteral reflux (1).